ARPIN (actin related protein 2/3 complex inhibitor)
Description:
Regulates actin polymerization by inhibiting the actin-nucleating activity of the Arp2/3 complex; the function is competitive with nucleation promoting factors. Participates in an incoherent feedforward loop at the lamellipodium tip where it inhibits the ARP2/2 complex in response to Rac signaling and where Rac also stimulates actin polymerization through the WAVE complex. Involved in steering cell migration by controlling its directional persistence.
Synonyms: C15orf38; MGC61550
Tractability: Small molecule: a structure with a bound ligand is known. PROTAC: ubiquitination databases record sites on it; its protein half-life has been measured.
Gene: Protein-coding gene on chromosome 15 (89,895,006 to 89,912,952, reverse strand). Ensembl gene ENSG00000242498.
Subcellular location: Cell projection, lamellipodium
Gene Ontology:
Molecular function: protein binding
Biological process: directional locomotion; negative regulation of actin nucleation; negative regulation of cell migration; negative regulation of lamellipodium morphogenesis
Cellular component: lamellipodium
Genetic constraint (gnomAD): Loss-of-function variants: 23 observed, 25.19 expected, observed/expected ratio (o/e) 0.91, 90% interval 0.66 to 1.29. The upper end of that interval is the gene's LOEUF score, 1.29, which puts it in group 5 of 6, group 1 being the genes least tolerant of losing a copy. Missense variants: 333 observed, 307.41 expected, observed/expected ratio (o/e) 1.08, 90% interval 0.99 to 1.19. Synonymous variants: 126 observed, 127.5 expected, observed/expected ratio (o/e) 0.99, 90% interval 0.85 to 1.15.
Homologues: Orthologues: chimpanzee ARPIN (98% identical), macaque AP3S2 (95% identical), pig ARPIN (91% identical), mouse Arpin (88% identical), dog ARPIN (88% identical), guinea pig ARPIN (84% identical), rabbit ARPIN (68% identical), tropical clawed frog ap3s2 (64% identical), zebrafish arpin (59% identical), rat Arpin (59% identical).
Diseases named in the same sentence as ARPIN in open-access papers:
ARPIN is named in the same sentence as 5 diseases in open-access papers, as found by Europe PMC text mining. Sharing a sentence is not in itself a finding about the gene and the disease. The quoted sentences say what the papers report.
type 2 diabetes (3 papers, 2017 to 2024). "For example, rs2028299, previously associated with type 2 diabetes, was an edQTL in the transcript of ARPIN, suggesting dysregulation of RNA editing as the cause of increased disease risk." (PMID 29527417, 2018). "rs2028299 is associated with type 2 diabetes and had two edQTLs in visceral fat (both located in the 3′ UTR of ARPIN)." (PMID 29527417, 2018).
ARPIN also shares sentences with these, for which no sentence is quoted: Anxiety (1 paper); breast carcinoma (1); cancer (1); Hyperglycemia (1).